CDKN1C (cyclin dependent kinase inhibitor 1C)
Diseases named in the same sentence as CDKN1C in open-access papers (continued):
Sharing a sentence is not in itself a finding about the gene and the disease.
cancer (continued). "Hereditary kidney cancer patients occupy 5–8% in all the diagnosed ones, and commonly harbor some cancer predisposition genes, such as TSC1/2, CDKN1C and DIS3L2." (PMID 34193180, 2021). "Apart from Cdkn1c, other cancer-related genes, such as RASSF7 and GPRC5A has also been linked with Klf5 in this study." (PMID 33923166, 2021). "We observed that samples with high chromatin accessibility of CERES have high expression of CDKN1C, accompanied by low expression of genes involved in cancer cell proliferation (MKI67 and PCNA) and aggressiveness (FOXM1)." (PMID 34272384, 2021). "KCNQ1 Opposite Strand/Antisense Transcript 1 (KCNQ1OT1) encodes a lncRNA from the opposite strand of KCNQ1 in the CDKN1C/KCNQ1OT1 cluster that is reported to play a vital role in the development and progression of cancer." (PMID 34827600, 2021). "The different roles of CDKN1C under different conditions reflects the complex and coordinated network that exist during cancer development, with its mechanism of action undergoing a series of changes due to environmental influences." (PMID 34283053, 2021). "This discovery is related to the inhibition of key Myc oncogene and the enhancement of CDKN1C (also known as p57) expression, which leads to proliferation inhibition and the apoptosis of cancer cells." (PMID 34203243, 2021). "Patients with 11p15 telomeric domain defects (H19/IGF2:IG-DMR -GOM and UPD) have a higher risk of developing cancer compared to cases presenting centromeric aberrations (KCNQ1OT1:TSS-DMR-LOM mutation and CDKN1C)." (PMID 33101381, 2020). "CDKN1C (also known as p57KIP2), one of the CDK inhibitors of the Cip/Kip family, has been associated with various cellular processes of cancer." (PMID 32308561, 2020). "Only few data are available on the ability of other polyphenols to promote CDKN1C transcription in cancer cell lines, favoring cell cycle arrest and apoptosis." (PMID 32933137, 2020). "A recent study has also shown that CDKN1C exhibits reduced mRNA expression in several human cancers." (PMID 32015692, 2020). "We identified a recurrent up-regulation of CDKN1C expression at the mRNA level in different cancer cell types silenced for ZBTB38 or its deubiquitinase USP9X." (PMID 30310057, 2018). "We then directly investigated the relationship between RBBP6, USP9X, ZBTB38, and CDKN1C expression and the clinical response to azacytidine in cancer patients." (PMID 30310057, 2018). "Recent studies have reported that miR-221 and miR-222 regulate cell growth and cell cycle progression by targeting cyclin-dependent kinase inhibitor 1B (CDKN1B) and cyclin-dependent kinase inhibitor 1C (CDKN1C) in several cancer cell lines." (PMID 23563786, 2013). "Gene targeting experiments have unambiguously shown that all three members are important players in tissue homeostasis and cancer whereas Cdkn1c is the only CKI to be uniquely required for embryonic development." (PMID 23341776, 2013). "The fact that epigenetic silencing of CDKN1C is so widespread in human cancer makes it an attractive target for epigenetic therapies." (PMID 19221586, 2009). "CDK inhibitor CDKN1C (p57KIP2) has been previously reported to be inactivated via promoter DNA methylation in a variety of human cancers." (PMID 19340297, 2009). "CDKN1C (p57Kip2) is commonly epigenetically silenced in cancer and is the only imprinted member of the CIP KIP family of cell cycle inhibitors." (PMID 19221586, 2009). "Methylation of this region has previously been shown to correlate with silencing CDKN1C expression in cancer cell lines." (PMID 19221586, 2009). "CDKN1C mRNA levels in nine cancers ranged from 2 – 60% of normal and in one cancer was 282% of normal." (PMID 18325103, 2008). "AI/LOH at 11p15.5 occurred in 28/73 (38%) informative cancers, but CDKN1C itself underwent AI/LOH in only 3/16 (19%) cancers (p = ns)." (PMID 18325103, 2008).
cancer (continued). "We examined the CDKN1C mRNA level in 10 cancers using quantitative real-time PCR (qPCR), and the CDKN1C protein level in 20 cancers using immunohistochemistry (IHC)." (PMID 18325103, 2008). "We found reduced expression of CDKN1C in 9/10 (90%) cancers relative to its paired normal epithelium, and normalized against GUSB." (PMID 18325103, 2008). "In contrast, CDKN1C mRNA levels were reduced in 9/10 (90%) cancers (p < 0.0001), ranging from 2–60% of paired normal epithelium." (PMID 18325103, 2008). "Similarly, deposition of methyl marks on H3K27 within CDKN1C locus EZH1/2 is another key cancer-promoting epigenetic modification that downregulates p57KIP2 expression." (PMID 38561743, 2024). "We confirmed the key and central role of CDKN1C in this vulnerability through CRISPR knockout of CDKN1C which reversed the cell cycle arrest of DEX sensitive cancer cells while DOX-inducible constructs overexpressing CDKN1C in resistant NSCLC lines produced a strong growth inhibition phenotype." (PMID 37035141, 2023). "In the case of KCNQ1OT1, its role in locally silencing the expression of the neighboring tumor suppressor cyclin‐dependent kinase inhibitor 1C (CDKN1C) may account for its oncogenic deregulation in cancers." (PMID 34668345, 2022). "Thus, upregulation of CDKN1C leads to inhibition of markers involved in cell growth, differentiation, cell death, and angiogenesis in malignant tumors." (PMID 33912215, 2021). "Besides traditional TNM staging system, molecular subtypes and age, we integrated CDKN1C levels aimed to achieve the sufficient survival assessment for this heterogeneous cancer." (PMID 34464504, 2021). "CDKN1C mutations have also been correlated to several types of cancer, such as colorectal, lymph-hematologic, breast cancer, and it emphasizes the presence of commonalities features between BWS and cancer predisposition." (PMID 33101381, 2020). "However, CDKN1C has been reported downregulated in other type of cancer cells mainly by histone modifications operating in critical regions of its promoter." (PMID 29661169, 2018). "In addition, we demonstrated that the depletion of ZBTB38, or its regulator deubiquitinase USP9X, enhances the cytotoxicity of 5-azacytidine derivatives in different cancer and leukemia cells, which was concomitant with the enhanced expression of CDKN1C mRNA." (PMID 30310057, 2018). "A further putative mechanism at the basis of CDKN1C down-regulation might be related to an increased rate of protein degradation, mainly due to the Skp2 overexpression, as frequently observed in human cancers." (PMID 29614816, 2018). "We then investigated the expression of CDKN1C in different cancer cells by western blot." (PMID 30310057, 2018). "This may suggest that the pharmacological approach we have demonstrated for inhibiting EZH2 and reactivating CDKN1C might have broad application for cancer therapy." (PMID 19340297, 2009). "Given the involvement of EZH2 in CDKN1C repression, we took the advantage of Oncomine microarray database and asked whether their expression levels are reversely correlated in human cancer." (PMID 19340297, 2009). "The extent to which these CDKN1C-mDC4s may be similar to the myeloid-derived suppressor cells (MDSCs) observed in some pathological conditions, such as inflammation, chronic infection or cancer remains to be determined." (PMID 34777332, 2021). "Consistently, the expression of CDKN1C and KIT was lower in cancers, including KIRC, KIRP, and BRCA, while ICAM1, SSX2IP, and TNFSF10 were higher in cancers, including STAD and CESC, opposing the effects of miR-221/222-3p." (PMID 41602427, 2026). "We found that DEGs, such as CDKN1C, NEDD4L, PLK2 and SOX4, were closely related to the occurrence and development of malignant tumors." (PMID 38520027, 2024). "CDKN1C, a CDK inhibitor belonging to the Cip/Kip family, regulates various cancer hallmarks such as cell proliferation, cell cycle progression and apoptosis." (PMID 35612714, 2022).
cancer (continued). "CDKN1C (p57KIP2) belongs to the cyclin-dependent kinase (CDK) inhibitors of the Cip/Kip family, which participate in several cellular processes in human cancers." (PMID 32015692, 2020). "Interestingly, CDKN1C mutations are not frequently observed in cancers." (PMID 33117811, 2020). "The gene set enrichment analysis revealed that these interacting proteins also interacted with cancer-related proteins, including KISS1, TIMP2, MMP11, IGFBP1, EGFR, and CDKN1C." (PMID 32117443, 2020). "Further studies will be required to clarify the direct and indirect regulation of CDKN1C expression by ZBTB38 in normal and cancer cells." (PMID 30310057, 2018). "In these GBM iPSCs, the widespread resetting of epigenetic methylation occurred in cancer-specific methylation variable positions, the GBM tumor suppressor gene CDKN1C (p57Kip2), and testin LIM domain protein (TES)." (PMID 29259714, 2017). "Treatment of the cell line with ketamine, an NMDA (N-methyl-D-aspartate) receptor antagonist widely used as analgesic for cancer pain treatment, decreases the p300-recruitment on PVT1 promoter, thus inhibiting the lncRNA repressing activity on CDKN1C expression." (PMID 35456025, 2022). "Moreover, histone hypoacetylation (mainly H3K9/K14) in the promoter of CDKN1C induced by the overexpression of HDAC1 and HDAC2 in cancer cells is another reason for the low expression of CDKN1C in cancers." (PMID 34650035, 2021). "Additionally, miR-221 modulates several gene targets involved in cancer-related pathways, including PTEN (P13K/AKT/mTOR), CDKN1B/p27, and CDKN1C/p57." (PMID 31681762, 2019). "It should be considered, however, that the inconsistency of the methylation changes of the imprinted loci outside of 11p15.5 suggests that apart from H19/IGF2 and KCNQ1OT1/CDKN1C, the other imprinted genes do not likely act as drivers of cancer progression in WT." (PMID 33217932, 2020). "Specifically, CTD-2218G20.2 was predicted to interact with 86 proteins (Pearson correlation coefficient, PCC > 0.3), some of which, including PSG4, PSG5, and PSG7, could also interact with cancer-related proteins, including KISS1, TIMP2, MMP11, IGFBP1, EGFR, and CDKN1C." (PMID 32117443, 2020).
genetic disorder (4 papers, 2020 to 2025). "Mutations of CDKN1C, the gene encoding human p57Kip2, result in the development of different genetic diseases, including Beckwith–Wiedemann, IMAGe and Silver–Russell syndromes." (PMID 34299047, 2021). "p57Kip2 is encoded by the imprinted gene CDKN1C, which is the gene most frequently silenced or mutated in the genetic disorder Beckwith–Wiedemann syndrome (BWS), characterized by multiple developmental anomalies." (PMID 33117811, 2020).
colorectal (2 papers, 2013 to 2023). "CDKN1C is an important inhibitor of the cell cycle, whose loss of expression appears associated with colorectal carcinogenesis and poor prognosis." (PMID 37046605, 2023).
hematological cancer (1 paper, 2019). "Depletion of ZBTB38 increases the cytotoxic ability of DNMT inhibitors in different solid and hematological cancer cell lines by increasing the expression of Cyclin-Dependent Kinase Inhibitor 1C (CDKN1C) which opens up a new avenue to increase the therapeutic response to DNMT inhibitors." (PMID 31245293, 2019).
infection (1 paper, 2021). The state of being infected such as from the introduction of a foreign agent such as serum, vaccine, antigenic substance or organism. "Interestingly, in this present study, whereas PCPEC displayed a strong inflammatory response to infection, genes attributed to hypoxia were found to play a more prominent role during infection in HIBCPP cells (including ZFP36L1, MXI1, KLHL24, PNRC1, CDKN1C, and DUSP2)." (PMID 33763387, 2021).
metabolic disease (1 paper, 2019). A congenital disorder (due to inherited enzyme abnormality) or acquired (due to failure of a metabolically important organ) disorder resulting from an abnormal metabolic process. "Placental CDKN1C, PHLDA2 and IGF-2 levels monitoring may be useful for prediction and prevention of the development of SGA births and its related postnatal metabolic diseases." (PMID 31194812, 2019).
psychiatric disorder (1 paper, 2020). A disorder characterized by behavioral and/or psychological abnormalities, often accompanied by physical symptoms. "The possible role of derepression of the paternal Cdkn1c allele in the link between early-life adversity and aberrant brain development associated with psychiatric disorders thus warrants further investigation." (PMID 32024956, 2020).
CDKN1C also shares sentences with these, for which no sentence is quoted: Metaphyseal dysplasia (10 papers); adrenal hypoplasia congenita (6); overgrowth syndrome (5); macroglossia (4); lymphoma (3); MIRAGE syndrome (3); rhabdomyosarcoma (3); acute myeloblastic leukaemia (2); adrenocortical tumors (2); bone disorder (2); Cirrhosis (2); cleft palate (2); esophageal squamous cell carcinoma (2); growth failure (2); HELLP syndrome (2); hypertensive disorder (2); Hypoglycemia (2); Insulin resistance (2); ischemia (2); lymph node metastasis (2); Multiple Myeloma (2); myocardial ischemia (2); nasopharyngeal carcinoma (2); Noonan syndrome (2); pancreatic adenocarcinoma (2); pancreatic neuroendocrine neoplasm (2); small cell lung carcinoma (2); thyroid cancer (2); achondroplasia (1); adenocarcinoma (1).
A further 76 diseases each share a sentence with CDKN1C in 1 paper.